NLRP3 (NLR family pyrin domain containing 3)
Diseases named in the same sentence as NLRP3 in open-access papers (continued):
Sharing a sentence is not in itself a finding about the gene and the disease.
endothelial dysfunction (continued). "In metabolic disease, lipotoxicity, mitochondrial ROS, oxidized lipids, and crystalline cholesterol converge on NLRP3 across adipose, myeloid, and vascular compartments, driving endothelial dysfunction, plaque growth, and adverse cardiac remodeling." (PMID 41488670, 2025). "In a study, it was found that the release of monocyte-derived microparticles (a subset of EVs) can activate endothelial cells via the NLRP3 inflammasome, leading to endothelial dysfunction." (PMID 40520933, 2025). "We have previously reported the role of NLRP3 inflammasome activation in initiating endothelial dysfunction." (PMID 41323268, 2025). "In animal models of hypertension, such as spontaneously hypertensive rats and Ang II–infused mice, the NLRP3 inflammasome plays a central role in endothelial dysfunction (ED) and vascular remodeling." (PMID 40867825, 2025). "Evidence indicated that TMAO fostered endothelial dysfunction and vascular calcification through the activation of the NLRP3 inflammasome and NF-κB signaling." (PMID 41154676, 2025). "Downregulation of SIRT3 increases mtROS generation, accompanied by reduction of NO release and activation of NLRP3 inflammasome, whereas activation of SIRT3 by honokiol inactivates the NLRP3 pathway, thereby preventing endothelial dysfunction." (PMID 41323268, 2025). "TMAO also induces endothelial dysfunction by disrupting junction proteins, activating the NLRP3 inflammasome to release high-mobility group box 1 protein (HMGB1), and altering endothelial permeability." (PMID 40777990, 2025). "Oxidative stress is another major factor that contributes to endothelial dysfunction in inflammatory settings by activating the NLRP-3 inflammasome." (PMID 40107203, 2025). "NLRP3 acts as an intracellular sensor for danger signals and tissue injury, triggering inflammatory responses and contributing to endothelial dysfunction and T2DM pathogenesis." (PMID 40648980, 2025). "Increasing evidence has shown that NLRP3 inflammasome is a potential mediator of endothelial dysfunction." (PMID 39679710, 2025). "Endothelial dysfunction is widely considered to be an early and pivotal event in the activation of the NLRP3 inflammasome in T2DM." (PMID 40648980, 2025). "AChE and DGKZ directly modulate smooth muscle function, while NLRP3 inflammasome contributes to endothelial dysfunction and smooth muscle cell pyroptosis, and PLD2 is involved in angiotensin generation." (PMID 39981435, 2025). "Activation of the NLRP3 inflammasome and its downstream signaling molecules can recruit and activate leukocytes and platelets while inducing endothelial dysfunction, leading to the release of various pro-inflammatory and pro-coagulant factors." (PMID 40520933, 2025). "In summary, NLRP3 activation in ECs, contributes significantly to vascular inflammation and endothelial dysfunction, playing a crucial role in the progression of cardiovascular and inflammatory diseases such as atherosclerosis." (PMID 41439981, 2025). "Through caspase-1-dependent release of proinflammatory mediators, NLRP3 drives localised immune activation within vascular tissues, contributing to endothelial dysfunction and structural remodelling of the vascular wall." (PMID 41008547, 2025). "In recent 5 years, related studies such as vascular calcification, endothelial dysfunction, NLRP3 inflammation, ischemia-reperfusion injury, and heart failure have become new hotspots, and are currently in a burst phase." (PMID 38938744, 2024). "As mechanisms of CKD progression due to hyperuricemia, endothelial dysfunction induced by uric acid and activation of the Nod-like receptor protein 3 (NLRP3) inflammasome induced by urate crystals have been a focus of research." (PMID 38548844, 2024). "NLRP3 inflammasome activity and persistent T-cell activation indicate on going inflammation contributing to persistent endothelial dysfunction, potentially intensified by sustained viral immune response." (PMID 38867241, 2024).
endothelial dysfunction (continued). "Specifically, NLRP3 inflammasome-dependent pyroptosis triggers endothelial dysfunction, thereby acting as a catalyst for AS in these cells." (PMID 38681198, 2024). "NLRP3 inflammasome activation exacerbates oxidative stress and endothelial dysfunction, while inhibition of the NLRP3 inflammasome signaling pathway can ameliorate vascular dysfunction." (PMID 39070552, 2024). "PA also triggered inflammation and endothelial dysfunction, as evidenced by NLRP3 activation, upregulation of ICAM-1 (endothelial activation marker), and pyroptotic markers (NLRP3, GSDM-D, IL-1β, IL-18)." (PMID 39770410, 2024). "It is well known that endothelial dysfunction mediated by NLRP3-dependent pyroptosis is one of the main factors in the pathophysiology of hypertension." (PMID 39052650, 2024). "Consistent with the expression of endothelial dysfunction markers, increased pro-inflammation markers (NLRP3 inflammasome, TNF-α, and NF-κB) induced by d-flow accompanied with decreased expression of eNOS and anti-inflammatory marker TGF-β induced by OSS." (PMID 38646649, 2024). "Our study demonstrated that PA-induced endothelial dysfunction significantly increased expressions of NLRP3, ICAM-1, GSDM-D, and pro-inflammatory cytokines IL-1β and IL-18 in the HUVECs during PA-induced pyroptosis." (PMID 39770410, 2024). "NF-κB activation is also shown to activate inflammasomes (including NLRP3), pro-inflammatory cytokines, cell adhesion molecules (CAMs), and matrix metalloproteinases (MMPs), resulting in endothelial dysfunction, atherosclerotic plaque instability, and rupture." (PMID 39770410, 2024). "In step-flow chamber, d-flow markedly inhibited MerTK expression while induced endothelial dysfunction, indicating increased expression of pro-inflammatory signaling such as NLRP3 inflammasome (NLRP3, pro-IL-1β, and cleaved IL-1β), TNF-α, and NF-κB." (PMID 38646649, 2024). "The main mechanisms involved in MIRI and intertwined with NLRP3 include ROS production, calcium overload, mPTP opening, MiRNAs, and endothelial dysfunction." (PMID 37507935, 2023). "Furthermore, several signaling pathways, such as NLRP3 inflammasome, that are associated with the inflammatory response and the disrupted H2S bioavailability are postulated to be new indicators for endothelial cell inflammation and its associated endothelial dysfunction." (PMID 37374202, 2023). "Some botanical drugs can target NLRP3 during AS and exert their effects, as found in vivo, S. plebeia can improve high glucose-mediated endothelial dysfunction by inhibiting PKCβII-related NLRP3 inflammasome activation and NF-κB signaling." (PMID 37251336, 2023). "TMAO can activate the NLRP3 inflammasome and motivate inflammation, which results in the occurrence of endothelial dysfunction." (PMID 36987419, 2023). "Further studies have showed that ASA improves the endothelial dysfunction by targeting NLRP3 inflammasome through the ROS/TXNIP pathway." (PMID 35335908, 2022). "Several studies have demonstrated the capability of ASA to attenuate the hepatotoxicity and endothelial dysfunction by regulating the NLRP3 inflammasome and IL-1β levels." (PMID 35335908, 2022). "Together, these results indicated that raltegravir reduced endothelial permeability and alleviated endothelial dysfunction via inhibiting NLRP3 activation." (PMID 36350972, 2022). "The mechanism by which TMAO activates NLRP3 inflammasome has been extensively investigated in recent years, which involves in oxidative stress aggravation and, ultimately, endothelial dysfunction." (PMID 36082127, 2022). "In dengue haemorrhagic fever, a study showed that its endothelial dysfunction was attenuated by dengue envelope protein domain 3 through NLRP3 inflammasome activation." (PMID 35528818, 2022). "It has been well-established that the activation of the NLRP3 inflammasome is an important initiating mechanism leading to endothelial dysfunction." (PMID 35874841, 2022).
endothelial dysfunction (continued). "Accumulating studies have shown that the NLRP3 inflammasome also plays an important role in endothelial dysfunction." (PMID 35844498, 2022). "In another study, NaHS was reported to improve endothelial dysfunction by inhibiting the NLRP3 inflammasome and oxidative stress in SHRs." (PMID 36034427, 2022). "TMAO has been reported to trigger activated NLRP3 inflammatory corpuscles in a dose-dependent and time-dependent manner to induce vascular inflammation, endothelial dysfunction, and ROS production." (PMID 36710972, 2022). "Many studies have indicated that the NLRP3 inflammasome links inflammatory stimuli to endothelial dysfunction." (PMID 35874841, 2022). "As studies have shown that the NLRP3 inflammasome complex is critical for initiating inflammatory responses and plays a role in endothelial dysfunction, inhibitors that target the NLRP3 inflammasome have been overwhelmingly outperformed." (PMID 35528818, 2022). "We also demonstrate reports showing that the expression of a few microRNAs that are also known to be involved in either NLRP3 inflammasome activation or endothelial dysfunction is deregulated in T2DM." (PMID 33546399, 2021). "We further showed that exercise training ameliorated ER stress-associated endothelial dysfunction in coronary arterioles in ApoE KO mice by reducing ER stress and TXNIP/NLRP3 inflammasome signaling." (PMID 34326395, 2021). "This drug works by improving endothelial dysfunction and has also been described as an inhibitor of NLRP3 in endothelial cells in the blood–brain barrier." (PMID 34831052, 2021). "But the potential impact of NLRP3 inflammasome activation in highly specialized brain EC on IS-induced endothelial dysfunction and subsequent BBB breakdown had remained elusive." (PMID 34930895, 2021). "Up until now, there were four miRNAs reported to play regulatory roles in T2DM as well as endothelial dysfunction and NLRP3 inflammasome, i.e., miRNA-9, miRNA-21, miRNA-133, and miRNA-146a." (PMID 33546399, 2021). "Previous vascular functional studies confirmed that NLRP3 inflammasome plays a pivotal role in the regulation of endothelial dysfunction by activation of caspase-1, IL-1β, and IL-18 in metabolic disease models." (PMID 34326395, 2021). "Overall, we determined that, in addition to what has been observed for endothelial cells and macrophages, SCAP also regulates the activation of the NLRP3 inflammasome in VSMCs, thus inducing endothelial dysfunction and enhanced atherosclerotic progression." (PMID 34094640, 2021). "TNFα induced endothelial dysfunction also significantly increased mRNA levels of IL-6, NLRP3 and PTGS2." (PMID 34362171, 2021). "This article aims to summarize the role of NLRP3 in PE related to endothelial dysfunction and oxidative stress, proposing different approaches for future therapies." (PMID 34831052, 2021). "There have been a few dozens of miRNAs reported to be involved in either regulating the NLRP3 inflammasome or developing inflammation, endothelial dysfunction, or T2DM." (PMID 33546399, 2021). "In this way, ROS mediate the interaction between NLRP3 inflammasome and endothelial dysfunction, being the first participant in the NLRP3 activation, promoting inflammation, and activating immune responses." (PMID 34831052, 2021). "It is also known that NLRP3-dependent pyroptosis in endothelial cells mediates endothelial dysfunction, which is one of the greatest contributors to the pathogenesis of hypertension." (PMID 33494430, 2021). "A study demonstrated that NLRP3 inflammasome played an important role in neointimal hyperplasia and endothelial dysfunction, while oleanolic acid administration attenuated carotid artery injury in diabetic rats through suppressing NLRP3 inflammasome." (PMID 34631209, 2021). "The aim of this work is to present a review of links between the NLRP3 inflammasome, endothelial dysfunction, and T2DM." (PMID 33546399, 2021).
endothelial dysfunction (continued). "Recently, several studies have shown that TMAO exacerbates cardiac fibrosis, vascular calcification, and endothelial dysfunction by activating the NLRP3 inflammasome." (PMID 34220546, 2021). "In this review, we present the important role of NLRP3 activation in exacerbating oxidative stress and endothelial dysfunction." (PMID 34831052, 2021). "Excitingly, the expanding research on the role of NLRP3 inflammasome in endothelial dysfunction will hopefully enrich the understanding of the vital role of NLRP3 inflammasome in endothelial dysfunction-related inflammatory diseases." (PMID 32948742, 2020). "The findings reviewed here highlight the tremendous potential of direct or indirect modulation of NLRP3 inflammasome activation in combating various endothelial dysfunctions." (PMID 32948742, 2020). "In this review, we attempt to summarize the latest progress and development trends in the NLRP3 inflammasome research, highlighting its role in redox regulation and endothelial dysfunction." (PMID 32948742, 2020). "In recent years, a group of evidence has accumulated linking NLRP3 inflammasome activation to the control of endothelial dysfunction." (PMID 32948742, 2020). "The protective mechanisms of other effective drugs have been shown to prevent endothelial dysfunction related to NLRP3 inflammasome, such as Asprin20 and puerarin." (PMID 32573820, 2020). "Straight after the shallow relationship between AE and NLRP3 inflammasome, we intended to further confirm the role of NLRP3 inflammasome on Ang II‐induced endothelial dysfunction in AE group." (PMID 32573820, 2020). "Collectively, this summary provides recent developments and perspectives on how NLRP3 inflammasome interferes with endothelial dysfunction and the potential research value of NLRP3 inflammasome as a potential mediator of endothelial dysfunction." (PMID 32948742, 2020). "These in vitro functional experiments suggest that 13-MB improves endothelial dysfunction by inhibiting NLRP3 inflammasome activation via autophagy induction." (PMID 31993073, 2020). "A large number of inhibitors have been demonstrated to improve endothelial dysfunction by inhibiting NLRP3 inflammasome signaling pathway, including endogenous and exogenous inhibitors, but with low specificity." (PMID 32948742, 2020). "While our understanding of the influence of NLRP3 inflammasome activation on endothelial dysfunction is continuously growing, our ideas on how NLRP3 inflammation perceives information about different mediators are still limited." (PMID 32948742, 2020). "Accordingly, the mutual promotion between mitochondrial dysfunction and ER stress contributes to the activation of NLRP3 inflammasome and endothelial dysfunction, both of which are involved in oxidative stress and the production of ROS." (PMID 32948742, 2020). "ER stress has been proven to activate NLRP3 inflammasome and promote the development of endothelial dysfunction." (PMID 32948742, 2020). "It is possible that 13-MB promoted protective autophagy in endothelial dysfunction by inhibiting the NLRP3 inflammasome." (PMID 31993073, 2020). "Endothelial dysfunction contributes to hypertension, and previous studies have found that elevated blood pressure was accompanied by increased levels of the NLRP3 inflammasome." (PMID 33633569, 2020). "A recent study showed that NLRP3 inflammasome activation during the EMT linked inflammatory injury and endothelial dysfunction." (PMID 32226786, 2020). "Simvastatin has been demonstrated to ameliorate endothelial dysfunction by inhibiting the activation of NLRP3 inflammasome in HG conditions." (PMID 32948742, 2020). "Taken together, these findings pointed at NLRP3 inflammasome activation as a major mechanism mediating the endothelial dysfunction and defective relaxation evoked by visfatin/eNampt infusion in vivo." (PMID 32214150, 2020).
endothelial dysfunction (continued). "And activation of NLRP3 inflammasome in vascular endothelial cells eventually leads to endothelial dysfunction and contributes to the development of cardiovascular diseases." (PMID 31412804, 2019). "We also examine how gut dysbiosis may contribute to systemic inflammation through lipopolysaccharide translocation, NLRP3 inflammasome activation, and endothelial dysfunction." (PMID 41897337, 2026). "Activation of NLRP3 in the placenta, uterus, kidneys, and maternal endothelium leads to the production of pro-inflammatory cytokines (IL-1β and IL-18) and triggers processes such as endothelial dysfunction, sodium retention, and hypertension." (PMID 40867825, 2025). "GLP-1 RAs also downregulate the NLRP3 inflammasome complex, a critical mediator of high glucose-induced endothelial dysfunction, by suppressing NLRP3, ASC, and caspase-1 expression and reducing oxidative stress via the inhibition of NADPH oxidase 4 (NOX4) in human umbilical vein endothelial cells." (PMID 40807170, 2025). "Smoking-induced atherosclerosis is associated with not only ROS formation and reduced NO availability but also with activation of matrix metalloproteinases (MMPs) to promote plaque formation, pro-inflammatory cytokines, and the NLRP3 inflammasome, contributing to further endothelial dysfunction." (PMID 39941130, 2025). "NLRP3 inflammasome activation leads to senescence and endothelial dysfunction." (PMID 41323268, 2025). "Yimusake may ameliorate endothelial dysfunction in DMED by down-regulating the NLRP3 inflammasome–mediated NF-κB signaling pathway and inhibiting oxidative stress." (PMID 41090037, 2025). "Our previous study focused on the pyroptosis and necroptosis pathways in DMED,12,13 whereas the current work specifically explores the role of the NLRP3 inflammasome–mediated NF-κB pathway and oxidative stress in endothelial dysfunction, providing a new mechanistic perspective for this field." (PMID 41090037, 2025). "Beyond acknowledging psychosocial risk, the model’s novelty lies in specifying the lipid-specific crosstalk with stress biology—for example, stress-triggered NLRP3 inflammasome activation and oxidative stress that converge on endothelial dysfunction to amplify lipid-driven atherothrombosis." (PMID 41156076, 2025). "Most randomized trials, including CANTOS, COLCOT, and LoDoCo2, initiated therapy days to weeks after the index event, well beyond the 3-to-7-day peak of inflammatory activity when NLRP3 activation, NETosis, endothelial dysfunction, and defective resolution are most modifiable." (PMID 41302946, 2025). "Whereas traditional models treat psychosocial stress as a contextual factor, our model emphasizes its role as a biological amplifier of lipid-driven atherothrombosis—through neuroendocrine activation, NLRP3 inflammasome signaling, oxidative stress, and endothelial dysfunction." (PMID 41156076, 2025). "Additionally, TMAO activates the NLRP3 inflammasome, triggering the release of pro-inflammatory cytokines, exacerbating endothelial dysfunction, and impairing NO-mediated vasodilation." (PMID 40278349, 2025). "Similarly, aerobic exercise also can inhibit the thioredoxin interacting protein (TXNIP)/NLRP3 inflammasome pathway and alleviate endothelial dysfunction in atherosclerotic coronary arterioles." (PMID 38681198, 2024). "Meg3 could promote Nlrp3-mediated inflammation in microglia, and its elevated expression could induce endothelial dysfunction." (PMID 39156629, 2024). "Considering NLRP3 inflammasome as a key driver of vascular disease and endothelial dysfunction suggests the implication of Cx43 hemichannels, which might be therapeutic targets." (PMID 38542257, 2024). "Research conducted in male rats with increased circulatory ADMA levels exacerbated endothelial dysfunction by implementing changes to the gut microbiota composition and intestinal and dorsal hippocampal NLRP3 activation, eventually resulting in cognitive impairment." (PMID 38542344, 2024).